BRAF (B-Raf proto-oncogene, serine/threonine kinase)
Diseases named in the same sentence as BRAF in open-access papers (continued):
Sharing a sentence is not in itself a finding about the gene and the disease.
melanoma (continued). "We propose a restricted panel for BRAF, KRAS/NRAS, KIT, CCDN1, and CDK4 mutations in the routine diagnostic test in order to better classify the SNM subtypes of melanoma." (PMID 31581559, 2019). "Mutations in EGFR, KRAS and driver mutations in ALK, BRAF, PIK3CA, AKT1, MAP2K1, and MET in NSCLC are also examples of predictive biomarkers as well as BRAF mutation in melanoma." (PMID 31547595, 2019). "Overall, the tumor genetic landscape for patients with BRAF- and NRAS-mutated melanoma was concordant with that reported in TCGA melanoma cases." (PMID 30956763, 2019). "The role of this lncRNA in melanoma has promising therapeutic implications since the combination of inhibitors of both BRAF and SAMMSON in pre-clinical models apparently exert a synergistic anti-tumor effect." (PMID 31861757, 2019). "Blockade of FGF/FGFR signaling by genetic constructs or kinase inhibitors inhibited melanoma growth, and synergistic anti-melanoma effects were obtained in vitro and in vivo if BRAF inhibitors were combined with FGFR inhibition." (PMID 31167513, 2019). "Personalised medicine targeted to specific biomarkers such as BRAF and c-Kit has radically improved the success of melanoma therapy." (PMID 30735560, 2019). "The adaptive resistance to BRAF inhibitors was reported to result in the promotion of PD-L1 expression in melanoma cells." (PMID 30842489, 2019). "A previous study showed that cold aqueous and crude methanol CN leaf extracts induced apoptosis in a wild type BRAF melanoma cell line (D24) in a dose- and time-dependent manner." (PMID 30806066, 2019). "We also observed that inhibitor of differentiation 3 (ID3), which belongs to the helix-loop-helix (HLH) TF superfamily, is upregulated in the tumors of melanoma patients after their treatment with a BRAF inhibitor, when compared to before the treatment." (PMID 31118886, 2019). "BRAF induces anoikis resistance by modulating Bad and Bim signaling in melanoma cells, whereas in CRC cell lines, MCL1 upregulation via MEK/ERK signaling was identified as a factor for anoikis resistance." (PMID 31545494, 2019). "The treatment options for patients with advanced, unresectable, or metastatic melanoma, especially BRAF-V600E/K mutant melanoma which comprises ~50% of the cases, have changed dramatically over a short period of time." (PMID 30800130, 2019). "In one study, researchers found that melanoma cells that acquired resistance to combined BRAF- and MEK- targeted therapy displayed robust drug addiction and were exquisitely sensitive to acute drug withdrawal." (PMID 34322663, 2019). "Here, we established three BRAFi‐R melanoma cell lines through chronic exposure of parental HTB63, A375 and A2058 melanoma cells to the PLX4032 BRAF inhibitor." (PMID 30582770, 2019). "Recently, to reduce pharmaceutical expenditure, a combination of 2 SMIs blocking 2 mutated genes (BRAF and MET) are performed in the unique formulation (encorafenib + binimatenib) for melanoma therapy." (PMID 31357735, 2019). "Firstly, the BRAF status is determined; then, the RAS status, then NF1, and c-kit mutations are considered for acrolentiginous melanomas." (PMID 30357519, 2019). "They observed that the expression levels decrease from nevi to stage III/IV melanoma samples and also that melanoma cell lines resistant to BRAF/MEK inhibitors showed a downregulation of this miRNA." (PMID 30499222, 2019). "Clinical trials performed both in melanoma and thyroid cancer patients showed encouraging results when BRAF-inhibitors were tested alone or in combination with other drugs." (PMID 31762942, 2019). "This study is the first to demonstrate the pharmacological activities of CUMA against drug resistant BRAF mutant melanoma." (PMID 30745871, 2019).
melanoma (continued). "In BRAF-driven melanomas, combination of BRAF, MEK, and immune checkpoint inhibition through PD-L1 inhibitors enhanced cancer cell death and displayed efficacy in early clinical trials for metastatic melanoma." (PMID 31681559, 2019). "The authors have correlated these adaptations with a mechanism of acquired resistance to BRAF inhibitors and suggested that intercellular communication mediated by such EVs is likely to be important for melanoma progression." (PMID 31861757, 2019). "Since then, genetic analysis showed an atypicalG464E mutation in the BRAF P loop region, accompanied by an enhancing G12D KRAS common oncogenic mutation which adds to higher c-MYC expression in C8161 melanoma compared to A375 cells." (PMID 30792807, 2019). "A recent clinical trial demonstrated significant improvement in both relapse-free survival and overall survival with adjuvant dabrafenib (BRAF inhibitor) plus trametinib (MEK inhibitor) in patients with stage III melanoma." (PMID 30725205, 2019). "Accordingly, with respect to BRAFV600E-mutated melanoma, both phosphorylation of ETS1 and upregulation of GABPB via Fos have been shown to link oncogenic BRAF signaling to activation of the mutant TERT promoter." (PMID 31391125, 2019). "In BRAF(V600E) melanoma cells, for example, activated ERK has been shown to phosphorylate LKB1, rendering this enzyme unable to bind to and activate AMPK." (PMID 30487597, 2019). "We used the peptide conjugates to treat the B-Raf inhibitor resistant MM415 (human malignant melanoma, BRAF wt, KRAS wt, NRAS Q61L) cell line." (PMID 30909892, 2019). "A major challenge for targeted therapy in BRAF-mutant melanoma is the development of secondary resistance." (PMID 31227006, 2019). "In another study on 101 advanced melanoma patients with decreased serum LDH after BRAF inhibitor treatment who completed all courses of ipilimumab, showed a significantly longer OS compared to those who did not (median OS 12.7 months vs. 1.2 months)." (PMID 31817189, 2019). "The microRNAs, miR-125a, miR-204, and miR-211 have been proposed as key players in the acquired resistance to BRAF inhibitor in melanoma, highlighting the clinical relevance of miRNA in cancer therapy." (PMID 31835496, 2019). "The availability of advanced proteomic and high-resolution nano-LC-MS/MS techniques has enabled the deeper mining of melanoma proteome analysis and the determination of the relative abundance of BRAF V600E protein expression across patient tumor metastases." (PMID 31835364, 2019). "The BRAF essentiality score is lower in mutant melanoma lines when processed with all lines compared to when processed with melanoma lines alone (median, −0.86 vs. −1.11)." (PMID 30674557, 2019). "To do so, we mapped differentially expressed genes in the combination treatment A375 cells relative to vehicle control onto the original BRAF melanoma network and observed that the majority (65%) of network genes were down-regulated." (PMID 30820351, 2019). "Systemic therapies for advanced melanoma have been dramatically revolutionized by the development of targeted therapies, such as BRAF and MEK inhibitors, and immunotherapies, such as anti-PD-1 antibodies alone or in combination with anti-CTLA-4 antibody." (PMID 30675668, 2019). "Recent publications have also shown that oncogenic BRAF gene fusions can also activate BRAF in melanomas and other cancers." (PMID 31426419, 2019). "The kinetics of ctDNA derived from each cancer type were monitored targeting BRAF V600R (melanoma) and KRAS G13D (colon cancer), specifically reflected the status of the patient’s tumours." (PMID 31727009, 2019). "Total RNA was isolated from plasma samples collected from 58 advanced BRAF-mutant melanoma patients and 15 healthy donors." (PMID 31231466, 2019). "In the literature, many promising therapies that are able to overcome drug resistance in mutant BRAF melanoma cells can be found." (PMID 31877948, 2019).
melanoma (continued). "Adults with BRAF mutated melanoma have higher responses rates and prolonged PFS and OS when treated with combination therapy compared to BRAF inhibitor monotherapy." (PMID 30728904, 2019). "Therapeutic interventions in melanoma are evolving rapidly, leaving behind questions about the role of metastasectomies in the era of immunotherapy and BRAF-MEK-targeted therapy and how we can better identify those patients who will develop hyper-progression." (PMID 30899610, 2019). "In this real‐world, retrospective analysis, patients with advanced BRAF V600 mutant melanoma treated with front‐line immunotherapy had longer overall survival as compared to those treated with front‐line BRAF/MEKi." (PMID 31677253, 2019). "Our study indicates that 17-aminogeldanamycin takes several advantages compared with other HSP90-targeting compounds, and can complement activity of BRAF/MEK inhibitors in melanoma cells of different genetic subtypes." (PMID 30989459, 2019). "The results of adult melanoma studies demonstrating that combination therapy with BRAF inhibitors and MEK inhibitors results in prolonged survival led us to employ this treatment strategy in children with BRAFV600E mutated HGG." (PMID 30728904, 2019). "In melanoma patients and in preclinical models using human xenografts, combined inhibition of BRAF and MEK achieves synergistic anti-cancer responses." (PMID 30718660, 2019). "BETi can synergize with BRAF inhibitors (BRAFi) in melanoma and colorectal cancer models and can re-sensitize BRAF-mutant cancer cells become resistant to BRAFi." (PMID 30841549, 2019). "Magnolol, 5,5'‐di‐(tert‐butyl)‐biphenyl‐2,2'‐diol and honokiol were found to be very effective to kill BRAF/NRAS‐mutant melanoma cells at a concentration of 30 μmol L−1 in comparison with 2‐Ome‐3’‐NHAc‐HK and Magreth‐26a‐1‐H." (PMID 30793515, 2019). "Conversely, the CheckMate- 067 trial with nivolumab showed that BRAF-mutant patients achieved a higher 2-year survival rate than wild-type melanomas (62% versus." (PMID 31179334, 2019). "Today, a phase II clinical trial of vemurafenib plus cobimetinib continuous vs intermittent in BRAF V600-mutant melanoma is ongoing (NCT02583516)." (PMID 31514399, 2019). "This study focused on preventing the increased invasive migration of BRAFi‐R melanoma cells; however, our combined treatment with an IL‐6 antibody and Box5 also restored the sensitivity of these cells to the BRAF inhibitor PLX4032." (PMID 30582770, 2019). "This work underpins the clinical relevance of CD271 and autophagy inhibition as a strategy to overcome the acquired resistance of BRAF‐mutant melanoma to mitogen‐activated protein kinase pathway inhibitors." (PMID 30339727, 2019). "This study thus defined SPRY4 as a potential mediator of synthetic suppression, which is likely to contribute to the observed exclusivity between BRAF(V600E) and NRAS(Q61R) mutations in melanoma." (PMID 30651601, 2019). "Further analysis demonstrated that the baseline lncRNAs for IGF2AS, anti-Peg11, MEG3, Zeb2NAT are independent prognostic factors in BRAF-mutant advanced melanoma patients treated with vemurafenib." (PMID 31231466, 2019). "Melanoma cell lines belonging to distinct mutational groups (BRAF-mutant, NRAS-mutant, or wild type for both BRAF and NRAS) co-expressed NFATc2 and EZH2 supporting the rationale for testing the potential anti-tumor effects of pharmacological co-targeting." (PMID 30710146, 2019). "This activity led to the suppression of protein expression and thus to interference with oncogenic signaling pathways involved in BRAF-mutant melanoma cell survival, apoptosis, and resistance to drugs." (PMID 31635389, 2019). "BRAF inhibitors have proven clinical activity in BRAF-mutant patients in other tumour locations, such as melanoma, but resistance emerges frequently due to a multitude of escape mechanisms, thereby necessitating combination treatment." (PMID 31353365, 2019).
melanoma (continued). "We next sought to functionally characterize if the ubiquitination-deficient BRAF mutant exhibits a compromised function in maintaining the growth and invasion of BRAFWT-expressing melanoma cells." (PMID 31015455, 2019). "Specifically, we simulated dual pan-ErbB and BRAF inhibition, and validated the model prediction of a synergistic increase in sensitivity of breast, colorectal, and melanoma cell lines to vemurafenib." (PMID 31672130, 2019). "In drug-naïve BRAFV600 melanoma cells, the RTK expression is low, probably because the strong endogenous BRAF/NRAS mutation-driven activation of the MAPK-ERK signaling pathway selects, against cells with active RTK signaling, to prevent senescence." (PMID 31167513, 2019). "Based on genomic analyses of the most prevalent mutations in the tumors (significantly mutated genes), the TCGA Research Network classified four molecular subtypes for melanoma patients: mutant BRAF, mutant RAS, mutant NF1, and Triple-Wildtype." (PMID 31747929, 2019). "Recently, transcriptional analysis has been used to define four different interlinked differentiation states for melanoma subtypes with differential resistance to drugs, such as BRAF inhibitors, and vulnerability to oxidative stress." (PMID 31257073, 2019). "We analyzed recently published RNA-seq data set from pre- and on-treatment tumor biopsies from seven melanoma patients treated with a BRAF inhibitors, MEK inhibitors, or a combination thereof." (PMID 31126321, 2019). "To characterize our forward mutagenesis screening system, we performed a screen to identify novel drivers of resistance to the BRAF inhibitor vemurafenib in cultured melanoma cells." (PMID 31208320, 2019). "A 23-year-old Asian male with metastatic BRAF-V600E melanoma was originally treated with B-Raf inhibitor + MEK inhibitor (trametinib and dabrafenib) and palliative radiation to a sacral metastasis." (PMID 31703593, 2019). "Mutations of key proteins in the RAS/RAF/MEK/ERK and PI3K/Akt/mTOR signaling cascades were described in malignant melanoma including BRAF (35–60%), NRAS (15–30%), and PTEN (8–15%)." (PMID 31623406, 2019). "We next determined the half-maximum inhibitory concentration (IC50) together with cell viability assays, and found that melanoma cells with BRAF mutant (V600E) under co-treatment of vemurafenib and melatonin was more sensitive to vemurafenib." (PMID 30717768, 2019). "What is the rate of cardiovascular adverse events among patients with melanoma treated with BRAF and MEK inhibitors compared with patients treated with BRAF inhibitor monotherapy?" (PMID 31397860, 2019). "We found that concomitant treatment of melanoma cells with inhibitors of BRAF and MCL-1 was also less effective than sequential treatment." (PMID 31727958, 2019). "BRAF promotes the transcription of a melanoma gene signature in embryonic neural crest progenitors, which later develop into tumors." (PMID 31108873, 2019). "Through our model of protein data in pan-cancer BRAF-V600E cells, vemurafenib sensitivity was accurately predicted in multiple tumor cell lines including colorectal, breast, bone, and melanoma tumors." (PMID 31672130, 2019). "While treatment of BRAFV600E–bearing tumors with BRAF inhibitors has a good response in melanomas, a protumor effect has been described in colon adenocarcinomas." (PMID 31001323, 2019). "Melanoma persister cells are tolerant to anti-BRAF and anti-MEK inhibition and can trigger cancer relapse." (PMID 31844050, 2019). "Recent advances in melanoma therapy have seen a shift away from BRAF targeted therapies toward those aimed at reactivating the immune system." (PMID 31207090, 2019). "The emergence of resistant cells has been observed upon treatment with chemotherapy, radiotherapy, and targeted therapies, including EGFR tyrosine kinase inhibitors in lung cancer, anti-HER2 therapies in breast cancer, and BRAF inhibitors in melanoma." (PMID 31355143, 2019).
melanoma (continued). "In fact, our results showed that the IHC method was valuable in identifying the presence of mutant BRAF V600E as a tumor marker in Iranian melanoma patients." (PMID 31531096, 2019). "In this context, the example of BRAF inhibitory drugs have been shown to be active in BRAF V600 mutated tumors, but when starting EXACT, approval of these drugs was limited to BRAF mutated melanoma." (PMID 30847023, 2019). "Our aim was to investigate the effects of long-term vemurafenib treatment on V600E BRAF-mutant pre- and post-treatment melanoma cell line pairs." (PMID 31514305, 2019). "BRAF mutant melanoma is an indication where clinical implementation of small molecule inhibitors targeting BRAF proved transformative; however, the majority of patients progress within the first year of treatment." (PMID 30824837, 2019). "BRAF inhibitors are clinically active in BRAF-mutant melanomas, but only in a fraction of patients and the effect is transient." (PMID 31391014, 2019). "Trials combining MEK and BRAF inhibition in melanoma have demonstrated modest clinical benefit; however, resistant tumors often have multiple different detectable MAPK mutations, suggesting convergent evolution." (PMID 30925887, 2019). "In a retrospective analysis of melanoma patients treated with pembrolizumab in second-line, the ORR was 26% for wild-type melanomas and 12% for BRAF-mutant patients." (PMID 31179334, 2019). "Our results show that transcriptomic and proteomic states are about equally predictive of drug sensitivity in our melanoma cell line panel, both being more predictive than genomic state, which was only predictive of BRAF inhibitor response." (PMID 31253656, 2019). "Based on the results of COLUMBUS trial, a phase III study of 577 patients with metastatic or unresectable melanoma harboring BRAFV600E mutation, the combination of encorafenib and binimetinib (a BRAF inhibitor) was approved by FAD in June 2018." (PMID 31134073, 2019). "When inhibitors of FGFR have been applied in parallel to BRAF inhibitors, the resistance of melanoma cells was diminished." (PMID 31167513, 2019). "We combined the BRAF inhibitor PLX4032 with S63845 in four BRAF mutant melanoma cell lines, but only observed enhanced killing over the individual drugs in the UACC 257 cells." (PMID 31019203, 2019). "Longitudinal ctDNA assessment predicts progression-free survival and overall survival in stage IV melanoma patients treated with BRAF and MEK inhibitors or immunotherapy and the melanoma-specific survival of patients with high-risk stage III resected melanoma." (PMID 31795494, 2019). "Largely, melanoma patients fall into 2 groups: BRAF wt and BRAF mutant, for which efficient targeted therapies exist." (PMID 30728057, 2019). "The predominance of genetic mechanisms converging on ERK reactivation has led to the successful use of dual MEK/BRAF inhibition in melanoma." (PMID 30341394, 2019). "BRAFV600E, or RAS with BRAF and NRAS mutated cell lines, showed higher levels of DUSP6 expression, compared to melanoma cell lines carrying wild type BRAF and NRAS." (PMID 31416288, 2019). "Most BRAF‐mutant melanoma patients experience a fulminate relapse after several months of treatment with BRAF/MEK inhibitors." (PMID 30793515, 2019). "Loss of CDK11 induces cell cycle dysfunction and death of BRAF- and NRAS-mutant melanoma cell lines." (PMID 30987032, 2019). "For example, BRAF-mutant melanoma cells have been reported to develop resistance to BRAF inhibitionin vivo due to “paradoxical” activation of melanoma-associated fibroblasts in the TME91." (PMID 31824652, 2019). "Here we show that a subpopulation of BRAFV600 mutant melanoma cells that tolerates exposure to BRAF and MEK inhibitors undergoes a reversible remodelling of mRNA translation that evolves in parallel with drug sensitivity." (PMID 31844050, 2019). "In recent years, several specific BRAF inhibitors (BRAFi) were developed and entered in clinical practice, mostly in melanoma." (PMID 31540406, 2019).